AURKA (aurora kinase A)
Diseases named in the same sentence as AURKA in open-access papers (continued):
Sharing a sentence is not in itself a finding about the gene and the disease.
tumor (continued). "Futhermore, immunohistochemical staining revealed decreased levels of FOXM1, AURKA and Nanog expression in Dox-induced tumours, compared with the control DMSO-treated cells." (PMID 28114286, 2017). "Collectively, these results support a functional role of the FOSL1 target AURKA in KRAS-driven tumours and unveil the dual inhibition of AURKA and MEK activation as a potential strategy to treat tumours with KRAS mutations." (PMID 28220783, 2017). "There was a positive correlation of AURKA with RACGAP1 gene expression in the tumor (r = 0.539, P < 0.001)." (PMID 26778597, 2016). "In contrast, tumour growth was observed in the CD24Low population when cell number was <1 × 105 and became more apparent when AURKA was overexpressed, suggesting that AURKA plays a role in tumour initiation." (PMID 26782714, 2016). "Although TC-A2317 was developed as a specific Aurora kinase A inhibitor, its anti-tumor effect has been investigated only in glioblastoma, and its mechanism has not been elucidated." (PMID 27713168, 2016). "The effect of AURKA on promoting tumour initiation was abolished by knocking down hnRNP K, further supporting the role of hnRNP K in AURKA-mediated BCSC property." (PMID 26782714, 2016). "Results from these experiments also established that the combination of AURKA inhibition (VX-680) and blocking AURKA nuclear localization had an additive tumour growth suppression effect (group 4)." (PMID 26782714, 2016). "We therefore studied the role of the FAK/PI3K/Akt pathway in dormant tumor cell revival, and the interactions between AURKA and this pathway in promoting LSCC metastasis." (PMID 27356739, 2016). "We regulated AURKA expression in tumor Hep2 (T-Hep2) and D-Hep2 cells to assess dormant tumor cell revival." (PMID 27356739, 2016). "Aurora kinase A inhibition by MK-5108 and alisertib increases the anti-tumor activity of docetaxel, paclitaxel, and vincristine, whereas Aurora A overexpression increases resistance to taxol." (PMID 27713168, 2016). "LS141 xenograft model at a dose of 30 mg/kg also showed efficient growth suppression by selective inhibition of Aurora Kinase A. Based on our data, a dose that can target only Aurora A will be more beneficial in tumor suppression." (PMID 26887042, 2016). "More importantly, Aurora kinase targeting reduced anchorage-independent growth of KRAS-transformed lung cells, and inducible inhibition of AURKA expression by RNA interference reduced A549 xenograft tumor growth in vivo." (PMID 26842935, 2016). "The hsa-let-7 family is well established as a tumor suppressor with interactions with cell cycle proliferative genes including Aurora Kinase A (AURKA), which it downregulates." (PMID 26717565, 2015). "In comparison with other treatments, the combination of AURKA siRNA and paclitaxel showed a tendency to inhibit tumor growth (P<0.1)." (PMID 25625960, 2015). "As observed in other GI cancers, suppression of AURKA using RNA interference or small molecule inhibitor SNS-314 suppresses tumor growth and enhances chemosensitivity." (PMID 25987188, 2015). "[11C]Alisertib accumulated in xenografts according to AURKA expression levels with highest albeit still modest tumor uptake and tumor-to-background ratios in A431 tumor (1.9% ± 0.2%ID/g at 25 p.i., 2.3 ± 0.8 ratio at 90 min p.i.)." (PMID 26690113, 2015). "As expected, an increasing level of AURKA and NDC80 as well as Ki-67 protein was associated with increasing tumor grades." (PMID 26468983, 2015). "We can not, however, exclude the possibility that germline polymorphisms in the mitotic checkpoint genes AURKA and BUB1B, despite being heterozygous, facilitated tumour formation." (PMID 26102504, 2015).
tumor (continued). "MLN8237, an AURKA selective inhibitor, was effective in stabilizing tumour volume and prolonged survival of mice with MPNST xenografts." (PMID 25026295, 2014). "For example, RHAMM silencing blocked the self-renewing capability of glioblastoma stem cells, and loss of RHAMM in malignant peripheral nerve sheath tumors or multiple myeloma enhances the sensitivity of tumor cells to AURKA inhibitors." (PMID 25157350, 2014). "For overall survival (OS), only large tumor size and AURKA overexpression were identified as independent unfavorable factors." (PMID 24901229, 2014). "Among 99 enrolled patients, poor performance status, large tumor size, drug response, and AURKA overexpression were independent prognostic factors for poor progression-free survival (PFS)." (PMID 24901229, 2014). "It is noteworthy that also one of its targets, i.e. the Aurora kinase A, is frequently overexpressed in tumours, indicating that both proteins are important for tumour formation or progression." (PMID 25401333, 2014). "In the multivariate analysis, however, only high AST level, tumor size greater than 11.5 cm, poor drug response, and AURKA overexpression were identified as independent prognostic factors for poor PFS." (PMID 24901229, 2014). "Tumour-bearing mice received oral doses of AURKA inhibitors, MLN8054 (60 mg/kg, QD), MLN8237 (30 mg/kg, QD) or vehicle control once daily." (PMID 23180582, 2013). "The identification of AURKA as a novel target of PTPRD mediated dephosphorylation adds to a growing list of substrates for this tumor suppressor." (PMID 22305495, 2012). "Immunohistochemical evaluation of phosphorylated AURKA protein was performed on 27 available tumour samples (20 with high AURKA-CN and 7 with low AURKA-CN)." (PMID 22240781, 2012). "In all, 1-year and 2-year survival were also longer among patients with high AURKA-CN tumours compared with those with low AURKA-CN tumours (1 year: 92.5% vs 82.2% P<0.001; 2 year: 80.9% vs 29.9%, P<0.001)." (PMID 22240781, 2012). "The goal in this study was to assess the frequency of increased AURKA-CN in archival tumour tissues of patients with metastatic CRC (mCRC) and correlate this finding with progression-free survival (PFS), overall survival (OS), and KRAS mutation status." (PMID 22240781, 2012). "In the multivariate Cox regression adjusted to age, grade and tumor size, AURKA showed independent prognostic significance in the ER+/HER2- subtype (HR 1.73; 95% CI 1.24–2.42; P=0.001)." (PMID 23186136, 2012). "Patients with high AURKA-CN tumours had longer median OS (48.6 vs 18.8 months, P=0.01), with stronger trend among KRAS wild-type tumours (median OS not reached vs 18.8 months, P=0.003)." (PMID 22240781, 2012). "Of the 61 tissue samples obtained for AURKA-CN analysis, 62% originated from primary tumours, while 38% originated from metastatic sites." (PMID 22240781, 2012). "For patients with high AURKA-CN tumours, the median PFS on first-line chemotherapy was 11.5 months vs 7.7 months for patients with low AURKA-CN tumours (HR=0.56, 95% CI: 0.28–1.1, P=0.094)." (PMID 22240781, 2012). "The improved OS for patients with high AURKA-CN was most pronounced in our study among patients with KRAS wild-type tumours." (PMID 22240781, 2012). "Increased AURKA-CN is common in mCRC tumours and is associated with longer OS and longer PFS during chemotherapy, particularly in KRAS wild-type tumours." (PMID 22240781, 2012). "Among patients with KRAS wild-type tumours, those with high AURKA-CN tumours had prolonged PFS compared with patients with low AURKA-CN tumours (HR=0.43, 95% CI: 0.19–0.94, P=0.04)." (PMID 22240781, 2012).
tumor (continued). "In our NSCLC patients' cohort, we observe a higher AURKA transcript level in tumor specimens against the corresponding morphologically normal adjacent lung tissues (Figure." (PMID 21718475, 2011). "AURKA expression was significantly up-modulated in tumor samples compared to matched lung tissue (p < 0.01, mean log2(FC) = 1.5)." (PMID 21718475, 2011). "Overall, this data supports the emerging network among genomic instability, AURKA over-expression and tumor progression in NSCLC." (PMID 21718475, 2011). "Some of the genes identified here are already used to predict tumor recurrence and the response to treatment, while AURKA and PLK1 are frequently included in "poor prognosis" signatures." (PMID 21352579, 2011). "Applying robust backward selection in a nested cross-validated fashion resulted in a highly compact model consisting of five variables: AURKA, tumor size, HER2, CD68 and nuclear grade." (PMID 20809974, 2010). "AURKA expression has prognostic value because it seems directly correlated to survival and it is frequently over-expressed in many tumours." (PMID 19753302, 2009). "Our demonstration of growth inhibitory activity of AURKA siRNAs suggests that this gene is essential for tumor cell growth and supports investigation of AURKA as an anti-tumor target." (PMID 19259408, 2008). "Beyond promoting tumor cell proliferation, migration, and invasion, AURKA may have a significant role in modulating antitumor immunity." (PMID 42111498, 2026). "PLK1, another key substrate of AURKA, is typically overexpressed in tumor cells." (PMID 41515655, 2026). "Compared with the NC group (0.9% saline solution), subcutaneous tumor growth was significantly suppressed in both the sh-AURKA group and the combination treatment group (sh-AURKA+ AS/BJO-NE group), with a more pronounced inhibitory effect observed in the combination group." (PMID 41471272, 2025). "INI1 directly governs and controls AURKA expression in tumor cells; however, in INI1‐deficient tumors such as EpS, the loss of INI1 leads to increased AURKA expression, creating an environment in which tumor cells become dependent on AURKA." (PMID 39789853, 2025). "Targeting AURKA may suppress tumor proliferation by promoting ciliogenesis, with compounds such as iCRT14, bexarotene, alisertib, and tubulin A identified as potential inhibitors." (PMID 40277920, 2025). "Additionally, we identified AURKA inhibitors as potential therapeutic option for tumours with alterations in tumour suppressors like FBXW7 or NSD1." (PMID 40775769, 2025). "This further supports the results of the previous transcriptome data analysis that AS/BJO-NEs may affect tumor development by decreasing the expression of AURKA and then downregulating the glycolysis level of OSCC through the PI3K/AKT pathway." (PMID 41471272, 2025). "The results revealed that AURKA was actively involved in the tumor immune microenvironment (TIME)." (PMID 40718709, 2025). "In addition to probing tumor-specific vulnerabilities, our screens identified AURKA, a prominent oncology target undergoing clinical evaluation, as a recurrent hit across all cell lines." (PMID 40180891, 2025). "It interacts with BRD4, and targeting both BRD4 and AURKA reduces tumor growth." (PMID 40949882, 2025). "In addition, the expression of AURKA was significantly associated with immune infiltration in HCC, and more immune cells and stromal cells infiltrated in tumor with high AURKA." (PMID 40311679, 2025). "Whether AURKA targeting could be an effective way to block RALA-dependent tumor growth is thus a question worth addressing." (PMID 40568758, 2025). "Targeting this pathway with the AURKA inhibitor PHA739358 in combination with Olaparib markedly suppressed tumour growth in both cell line derived and patient-derived xenograft models, underscoring a mechanistic and therapeutic convergence between AURKA and PARPi in MYCN-driven malignancies." (PMID 41561634, 2025).
tumor (continued). "Aurora Kinase A is a regulator of tumor progression and is overexpressed in GBM." (PMID 40336841, 2025). "For instance, AURKA inhibitors, effective in RB1 and PTEN mutant tumours, could be trialed in tumours with mutations in less-studied tumour suppressors, such as FBXW7 and NSD1, for which we found AURKA to be a key gene in classification." (PMID 40775769, 2025). "The PKC inhibitor GF109203X could play a key role in reducing AURKA dephosphorylation and inducing cell cycle G2/M arrest, thus restraining the development of NE characteristics and inhibiting tumor growth in vitro." (PMID 40746825, 2025). "These subsets had higher cell stemness and CNV events, suggesting that these AURKA-expressing subsets may promote tumor development and progression." (PMID 40718709, 2025). "Aurora kinase A (AURKA) is a therapeutic target in NE‐transformed tumors, as its inhibition both degrades the oncogenic driver N‐Myc and is synthetically lethal with RB tumor suppressor loss." (PMID 41415713, 2025). "Additionally, AURKA modulates survival signaling and apoptotic regulators to support tumor cell survival and inhibit apoptosis." (PMID 40949156, 2025). "Nude-mice transplanted tumor model was used for investigating the role of AURKA in ES in vivo." (PMID 38287009, 2024). "Recent insights into AURKA's role in modulating the tumour microenvironment, particularly immune cell recruitment, may provide valuable information for personalized treatment strategies." (PMID 38590119, 2024). "Notably, HSP70 inhibition significantly suppressed NEPC tumor growth, increased the efficacy of aurora kinase A (AURKA) inhibitors, and limited the expression of neuroendocrine-related pathways." (PMID 39103353, 2024). "Previous studies have reported the involvement of AURKA in tumor metabolism." (PMID 38521813, 2024). "Indeed, the dysregulated interaction between ncRNAs and AURKA contributes to tumor development, progression, and therapeutic resistance." (PMID 39598228, 2024). "The results showed that AURKA was positively located in the cytoplasm and nucleus of tumor cells." (PMID 39585848, 2024). "AURKA physiologically interacts with LKB1 and phosphorylates it at S299, which impairs the association of LKB1 with its main substrate, AMPK, which in turn inhibits LKB1’s tumor-suppressive roles, thereby facilitating NSCLC growth and migration." (PMID 39334449, 2024). "IHC was used to detect the expression of AURKA in NB tumor tissues from 77 patients." (PMID 39585848, 2024). "Therefore, SK-N-AS, a non-MYCN-amplified human NB cell line, was selected in this study to explore the role of AURKA in the regulation of tumor progression." (PMID 39585848, 2024). "In fact, while AURKA mRNA levels decrease by approximately 2–3 times in all cell lines upon KD, AURKA protein levels behave differently: they decrease by approximately 6–8 times in tumor lines but increase by 11 times in HMEC cells." (PMID 39000605, 2024). "This suggests that AURKA might be involved in tumor immune evasion, leading to a poor prognosis for patients with NB, and that AURKA inhibition could be helpful to improve the immunotherapeutic efficacy for NB." (PMID 39585848, 2024). "These discrepancies in the observed relationship between AURKA and PD-L1 may arise from differences in experimental systems, tumor types, and specific mechanistic details that warrant further in-depth investigation to fully elucidate the underlying mechanisms." (PMID 38995006, 2024). "Therefore, identifying specific tumor subtypes or indications that exhibit sensitivity to AURKA inhibitors is crucial for the potential application of AURKA inhibitor monotherapy." (PMID 38521813, 2024). "To assess whether combining AURKA inhibition with cisplatin or radiation increases its efficacy, we performed in vitro and in vivo studies investigating cell viability and tumor size." (PMID 39199578, 2024).
tumor (continued). "Hence, understanding the mechanisms of AURKA actions is essential for improving the efficacy of anti-tumor therapy and overcoming drug resistance." (PMID 38994036, 2024). "Notably, majority targets of TB-2 are implicated in tumor therapy, including TGM2, KIT, EGFR, AURKA, FASN, and CDK2, which have garnered extensive research attention." (PMID 39376614, 2024). "In addition, AURKA expression was correlated with tumor size (R = 0.21, P = 0.013), preoperative (R = 0.34, P < 0.001) and postoperative basal serum levels of calcitonin (R = 0.21, P = 0.012), and TILs (R = 0.44, P < 0.001)." (PMID 38903715, 2024). "Various viruses modulated AURKA to induce viral-mediated tumor." (PMID 41907711, 2024). "However, given the diverse mutation patterns observed in different tumor types, unbiased screens using multiple CRISPR/Cas9 libraries in additional tumor types are necessary to comprehensively explore indications for AURKA inhibitors." (PMID 38521813, 2024). "AURKA protein expression is often elevated within HCC tumours." (PMID 38590119, 2024). "In the in-house cohort, we demonstrated a significant association between AURKA gene expression and Aurora-A protein (IHC) positive tumor cell fraction (P = 0.004, ρ = 0.70, data not shown)." (PMID 39198859, 2024). "Moreover, dual AURKA and PD-L1 pharmacological blockade resulted in the strongest inhibition of tumor growth and organ metastatic burden." (PMID 38873259, 2024). "Aurora kinase A (AURKA) plays a pivotal role in regulating cell mitosis and tumor progression." (PMID 37965456, 2023). "Finally, we show that TPX2 contribution to AurkA nuclear localization has functional consequences in MCF10A cells on tumor-related AurkA roles." (PMID 36797043, 2023). "Pharmacological USP8 suppression elicits multiple tumor-inhibitory effects, likely through dysregulating various mRNA expression events, including that of the key cell cycle regulator and oncogenic protein AURKA." (PMID 36816802, 2023). "Elevated AURKA expression correlated closely with poorer prognosis and advanced tumor stages." (PMID 37965456, 2023). "Next, CPL304110 selectivity was analyzed on seven kinases; the results showed that CPL304110 had the highest activity against kinases that share homology with FGFRs (KDR and PDGFRβ) and others that play an important role in tumor development and progression (AURKA, FLT3, IGF1R, JAK2, and TRKA)." (PMID 38282676, 2023). "Given the important role of AURKA in tumor progression, we speculate that TIALD exerts the function of inhibiting metastasis via binding to AURKA." (PMID 37773181, 2023). "It has been shown that the AURKA activity is vital to promote colony formation and tumor growth." (PMID 36816802, 2023). "Finally, we substantiated the biological role of AURKA in three different tumor cell lines, encompassing EAC, PRAD, and PAAD, through various cellular phenotype experiments." (PMID 37965456, 2023). "The precise underlying mechanism by which AURKA drives NEPC remains unclear, but its amplification is associated with deregulated proliferation and aggressive tumor behavior." (PMID 37761978, 2023). "Moreover, it has been demonstrated that AURKA is a synthetic lethal partner of multiple tumor suppressors." (PMID 37174007, 2023). "Additionally, AURKA inhibition enhances T-cell cytotoxicity and augments anti-tumor immunity in vitro." (PMID 37965456, 2023). "Collectively, the present results demonstrated that high expression of AURKA may be an independent factor of poor prognosis in patients with GC, and CA significantly suppressed the tumor biological functions of GC and inhibited the AURKA/β-catenin/Wnt pathway." (PMID 36937887, 2023). "We further explored the relationship between AURKA and the UICC tumor stage, revealing that AURKA was linked to advanced tumor stages in ACC (p=0.0023), KIRC (p<0.001), LIHC (p=0.02), UCEC (p=0.018), KIRP (p<0.001), LUSC (p=0.049), LUAD (p=0.021), and TGCT (p=0.043)." (PMID 37965456, 2023).